NFE2 (nuclear factor, erythroid 2)
Description:
Component of the NF-E2 complex essential for regulating erythroid and megakaryocytic maturation and differentiation. Binds to the hypersensitive site 2 (HS2) of the beta-globin control region (LCR). This subunit (NFE2) recognizes the TCAT/C sequence of the AP-1-like core palindrome present in a number of erythroid and megakaryocytic gene promoters. Requires MAFK or other small MAF proteins for binding to the NF-E2 motif. May play a role in all aspects of hemoglobin production from globin and heme synthesis to procurement of iron.
Synonyms: NF-E2; p45
Tractability: PROTAC: UniProt records ubiquitination sites on it; ubiquitination databases record sites on it; a small molecule that binds it is known.
Target class: Transcription factor
Gene: Protein-coding gene on chromosome 12 (54,292,107 to 54,301,259, reverse strand). Ensembl gene ENSG00000123405.
Subcellular location: Nucleus, PML body; Cytoplasm
Subcellular location (Human Protein Atlas): Actin filaments; Nucleoplasm
Pathways (Reactome):
Gene expression (Transcription): RUNX1 regulates genes involved in megakaryocyte differentiation and platelet function
Hemostasis: Factors involved in megakaryocyte development and platelet production
Gene Ontology:
Molecular function: cis-regulatory region sequence-specific DNA binding; DNA binding; identical protein binding; protein binding; sequence-specific double-stranded DNA binding; WW domain binding; DNA-binding transcription factor activity; DNA-binding transcription factor activity, RNA polymerase II-specific; RNA polymerase II cis-regulatory region sequence-specific DNA binding; sequence-specific DNA binding
Biological process: hemostasis; integrated stress response signaling; nucleosome disassembly; positive regulation of DNA-templated transcription; regulation of transcription by RNA polymerase II; regulation of DNA-templated transcription
Cellular component: protein-DNA complex; RNA polymerase II transcription regulator complex; chromatin; nucleoplasm; nucleus; cytoplasm; PML body
Genetic constraint (gnomAD): Loss-of-function variants: 13 observed, 25.9 expected, observed/expected ratio (o/e) 0.5, 90% interval 0.33 to 0.8. The upper end of that interval is the gene's LOEUF score, 0.8, which puts it in group 3 of 6, group 1 being the genes least tolerant of losing a copy. Missense variants: 382 observed, 485.76 expected, observed/expected ratio (o/e) 0.79, 90% interval 0.72 to 0.86. Synonymous variants: 204 observed, 206.08 expected, observed/expected ratio (o/e) 0.99, 90% interval 0.88 to 1.11.
Gene-disease validity (ClinGen):
ClinGen rates the evidence that NFE2 causes each of these diseases.
thrombocytopenia (autosomal recessive): Limited. A reduction in the number of circulating thrombocytes.
Homologues: Orthologues: chimpanzee NFE2 (99% identical), macaque NFE2 (98% identical), dog NFE2 (92% identical), pig NFE2 (92% identical), guinea pig NFE2 (91% identical), rat Nfe2 (90% identical), mouse Nfe2 (89% identical), rabbit NFE2 (83% identical), zebrafish nfe2 (37% identical), tropical clawed frog nfe2 (32% identical). Paralogues in human: NFE2L2 (38% identical), NFE2L1 (36% identical), NFE2L3 (31% identical).
Diseases named in the same sentence as NFE2 in open-access papers:
NFE2 is named in the same sentence as 77 diseases in open-access papers, as found by Europe PMC text mining. Sharing a sentence is not in itself a finding about the gene and the disease. The quoted sentences say what the papers report.
myeloproliferative neoplasm (12 papers, 2015 to 2025). A clonal hematopoietic stem cell disorder, characterized by proliferation in the bone marrow of one or more of the myeloid (i.e., granulocytic, erythroid, megakaryocytic, and mast cell) lineages. "The histone demethylases KDM4C (JMJD2C) and KDM3C (JMJD1C) were recently identified as signaling effectors of mutated JAK2 and target genes of the transcription factor NFE2, which is overexpressed in myeloproliferative neoplasms." (PMID 40140631, 2025). "Histone demethylases KDM4C and KDM3C were recently identified as a signaling effector of mutated JAK2 and a target gene of the transcription factor NFE2, which is overexpressed in myeloproliferative neoplasms." (PMID 40374809, 2025). "Altered NFE2 activity predisposed to leukemic transformation and NFE2 is overexpressed in the majority of patients with myeloproliferative neoplasms." (PMID 35619054, 2022). "NFE2 (nuclear factor erythroid 2) is associated with myeloproliferative neoplasms and polycythemic disorders." (PMID 34793333, 2022). "In 2–3% of myeloproliferative neoplasms cases, truncating NFE2 mutations were identified and confer a proliferative advantage." (PMID 31896782, 2020). "This pathway regulates the expression of critical genes such as NFE2, overexpressed in most myeloproliferative neoplasms (MPNs), and NANOG, essential for cytokine independence." (PMID 40374809, 2025). "In contrast, mice expressing an Nfe2 transgene in hematopoietic cells exhibit many features of myeloproliferative disorders (MPN) including thrombocytosis and leukocytosis, and often develop acute myeloid leukemia or myelosarcoma." (PMID 33081224, 2020). "The transcription factor NFE2 is overexpressed in most patients with myeloproliferative neoplasms (MPN)." (PMID 36709354, 2023). "Nuclear factor-erythroid 2 (NFE2), a transcription factor overexpressed in myeloproliferative neoplasms and important for hematopoietic stem cell maintenance and differentiation, was down-regulated in HL-60 cells." (PMID 35359604, 2022).
Thrombocytopenia (10 papers, 2010 to 2025). "A deficiency in NFE2 can lead to severe thrombocytopenia in mammals, resulting in bleeding disorders due to impaired platelet production." (PMID 40937321, 2025). "Moreover, it was previously shown in mice and humans that mutations in Nfe2, Fli1 and Runx1 cause thrombocytopenia, and that promoter occupancies with NFe2, Fli1 and Runx1 correlated with terminal MK differentiation." (PMID 38067194, 2023). "However, NFE2-deficient mice develop severe thrombocytopenia arising from the intrinsic defects in the megakaryocyte lineage, indicating its indispensable role in megakaryocyte biogenesis." (PMID 33081224, 2020). "Mutations in mouse and human Nfe2, Fli1 and Runx1 cause thrombocytopenia." (PMID 27457419, 2016). "The results from both preclinical studies in rats and a human clinical trial with BMS-986158 treatment revealed that Nuclear Factor Erythroid 2 (NFE2) and Platelet Factor 4 (PF4, CXCL4) genes are desirable biomarkers for predicting the risk of thrombocytopenia following BET inhibition." (PMID 40937321, 2025). "This suggests that NFE2 may serve as a biomarker not only for thrombocytopenia but also for anemia, extending its relevance beyond BET inhibition." (PMID 40937321, 2025). "Early detection of transcriptional changes in blood samples during treatment courses positions NFE2 and PF4 as promising biomarkers for proactively monitoring and mitigating treatment-emergent thrombocytopenia." (PMID 40937321, 2025). "Our study demonstrates that BET inhibition induces thrombocytopenia in vivo by altering GATA1 gene expression and its downstream genes, NFE2 and PF4, which regulate megakaryopoiesis and thrombopoiesis." (PMID 40937321, 2025). "GATA1 affects NFE2 and PF4, influencing thrombopoiesis and leading to thrombocytopenia." (PMID 40937321, 2025). "Further investigation into the use of NFE2 and PF4 as early biomarkers could improve our ability both to predict and manage drug induced thrombocytopenia." (PMID 40937321, 2025). "Furthermore, our findings demonstrate the translatability of NFE2 and PF4 from preclinical to clinical settings, making them valuable tools for predicting and monitoring thrombocytopenia, and potentially anemia." (PMID 40937321, 2025). "Similarly, while the mutations of platelet genes Itga2b and Nfe2 confer PDA in mice but not humans, thrombocytopenia and various platelet indices correlate with PDA in preterm infants." (PMID 34350653, 2022).
leukemia (9 papers, 2017 to 2025). A malignant (clonal) hematologic disorder, involving hematopoietic stem cells and characterized by the presence of primitive or atypical myeloid or lymphoid cells in the bone marrow and the blood. "The top 15 TFs enriched within the K562 cell associated pattern include TAL1, EGR1, RREB1 and NFE2 which have all been associated with leukemia or, in the case of NFE2, is an erythroid nuclear factor." (PMID 32392348, 2020). "Transgenic mice overexpressing NFE2 as well as mice harboring NFE2 mutations display an MPN phenotype and spontaneously develop leukemia." (PMID 36709354, 2023). "These include mutations in genes known to cooperate with CBF-rearrangements [e.g. NRAS (n = 6), KRAS (n = 4), FLT3 (n = 2), KIT (n = 3), ZBTB7A (n = 2)] as well as in genes, which have not been described to be mutated in CBF leukemia so far (e.g. ZFHX4, NFE2, HERC1)." (PMID 31896782, 2020).
breast cancer (8 papers, 2016 to 2024). A primary or metastatic malignant neoplasm involving the breast. "Moreover, Nfe2 expression was associated with enhanced expression of Wnt-related molecules, suggesting that NFE2 can regulate the Wnt pathway, thereby contributing to breast cancer growth in a bone cavity." (PMID 33081224, 2020). "NFE2 can confer growth advantages on breast cancer cells under hypoxia and anchorage‐independent conditions, while TEAD4 expression is the most frequently observed among the four TEAD members in various types of cancers." (PMID 38501838, 2024). "In EA TNBC, this core set of EA-specific hypoxia response TFs once again included members of the AP-1 TF family, which have been found to be induced in hypoxic environments, as well as NFE2 and NF2L1/2 which have been linked to Wnt signaling in breast cancer." (PMID 37732899, 2023). "NFE2 promotes breast cancer cell growth in the bone microenvironment, which leads to bone metastasis; enhances expression of Wnt-related molecules." (PMID 35060926, 2022). "Alternatively, inhibition of Nfe2 expression can be employed to treat bone metastasis of breast cancer with aberrant Nfe2 expression." (PMID 33081224, 2020). "In this study, we revealed that a transcription factor, Nfe2, plays an indispensable role in breast cancer metastasis to bone, by conferring growth advantages to breast cancer cells in the bone microenvironment." (PMID 33081224, 2020). "In order to evaluate the clinical relevance of Nfe2 expression, we evaluated the data on overall survival of breast cancer patients." (PMID 33081224, 2020). "Through combined dry bioinformatics and wet analyses, Nfe2 has finally been identified as a transcription factor, which can provide breast cancer cells with an intraosseous growth advantage." (PMID 33081224, 2020). "Patients with a higher expression of Nfe2 exhibited an unfavorable prognosis, suggesting the clinical significance of Nfe2 expression among breast cancer patients." (PMID 33081224, 2020). "On the contrary, we provided the first definitive evidence to indicate that NFE2 was robustly expressed in mouse breast cancer cells grown in a bone cavity." (PMID 33081224, 2020). "Here, we proved that a transcription factor, NFE2, was expressed selectively in breast cancer cells at bone metastasis sites and contributed crucially to their enhanced proliferation therein, by activating Wnt pathway." (PMID 33081224, 2020). "Hence, we conducted GSEA on Nfe2-overexpression 4T1.0 clone and demonstrated, together with subsequent qRT-PCR analysis, the enrichment of Wnt pathway molecules in 4T1.3 clones grown in a bone cavity as well as Nfe2-expressing breast cancer cells." (PMID 33081224, 2020). "Thus, NFE2 can be a novel molecular target to treat breast cancer bone metastasis." (PMID 33081224, 2020). "Moreover, we proved that NFE2 could confer a growth advantage on breast cancer cells under hypoxic and anchorage-independent conditions, which mimic the microenvironment in a bone cavity." (PMID 33081224, 2020). "We finally provided evidence to indicate that Nfe2, a transcription factor involved in normal and malignant hematopoiesis, could provide breast cancer cells with an advantage to grow efficiently in a bone cavity, thereby accelerating breast cancer bone metastasis." (PMID 33081224, 2020). "With regard to DNA methylation expression levels, cg06807713, cg25721818, cg23384027, cg17869315, cg24087497 from NFE2; cg16861241, cg12284789, cg25051233 from FOXJ1 came up with the highest levels and significant prognostic values (likelihood ratio (LR) test P < 0.05) in breast cancer." (PMID 37596527, 2023).
Thrombocytosis (6 papers, 2016 to 2025). Increased numbers of platelets in the peripheral blood. "In this patient, we propose that augmented NFE2 activity through a gain-of-function, DNA-binding mutation drives thrombocytosis in absence of a classical MPN driver mutation." (PMID 41465537, 2025).
anemia (5 papers, 2015 to 2025). A reduction in the number of red blood cells, the amount of hemoglobin, and/or the volume of packed red blood cells. "Mutations or dysregulation of NFE2 can impair erythropoiesis, leading to anemia." (PMID 40937321, 2025). "This suggests that the up-regulation of NFE2 may be an in-flight response to counter space anaemia." (PMID 38862545, 2024).
COVID-19 (4 papers, 2022 to 2023). A disease caused by infection with severe acute respiratory syndrome coronavirus 2. "Accordingly, we believe that NFE2 activation may be a feasible adjuvant treatment for preventing periodontitis and COVID-19." (PMID 37495990, 2023). "Similarly, in clinical trial, NFE2 activator reduced lung alveolar cells damage in COVID-19 positive patients." (PMID 37495990, 2023). "For instance, IL1B, NFKB1, NLRP3, PYCARD, and CASP1 are listed in the COVID-19 Disease Map, while there are molecules absent from it, including CCL3, 3L1, 4L2, CXCL1, 2, 3, 5, 16, TNFAIP6, C15orf48, TMEM176A/B, NFE2, PADI4, RAB20, ETS2, PHLDA2, FOLR3, and HP." (PMID 37719701, 2023).
erythrocytosis (4 papers, 2022 to 2023). "Diseases associated with NFE2 include Erythroleukemia and Polycythemia." (PMID 36650426, 2023).
ovarian carcinoma (4 papers, 2017 to 2025). A malignant neoplasm originating from the surface ovarian epithelium. "The mRNA expression of NFE2 members was significantly correlated with the immune infiltration of CD4+ T cells, CD8+ T cells, B cells, macrophages and neutrophils in Ovarian Cancer." (PMID 36650426, 2023). "Unlike outcomes in the ovarian cancer study, most of the regulatory relationships here are linear, only IRF1 and NFE2 in Monocyte cell line show nonlinear regulations." (PMID 33256599, 2020).
acute leukemia (3 papers, 2015 to 2025). A clonal (malignant) hematopoietic disorder with an acute onset, affecting the bone marrow and the peripheral blood. "Elevated NFE2 expression and mutations in NFE2 strongly predispose for transformation to acute leukemia both in MPN patients and in murine models." (PMID 36709354, 2023). "NFE2 levels are increased in the majority of MPN patients, and transgenic mice expressing elevated NFE2 levels develop an MPN-like phenotype with spontaneous transformation to acute leukemia (AML), at a rate similar to that observed in MPN patients." (PMID 41465537, 2025). "Of these, the NFE2 mice consistently show spontaneous transformation to acute leukemia, suggesting that elevated NFE2 activity promotes not only MPN development but also a sustained acquisition of additional aberrations leading to leukemic transformation." (PMID 26543325, 2015). "Moreover, mutations in NFE2, found in a subset of MPN patients, strongly predispose for transformation to acute leukemia." (PMID 36709354, 2023). "A large majority of MPN patients display increased NFE2 levels and transgenic NFE2 overexpressing mice develop an MPN phenotype with spontaneous transformation to acute leukemia." (PMID 36709354, 2023).
acute myeloid leukemia (3 papers, 2015 to 2025). Acute myeloid leukemia (AML) is a group of neoplasms arising from precursor cells committed to the myeloid cell-line differentiation. "Moreover, NFE2 mutations, found in a subset of MPN patients, augment NFE2 activity and are associated with a markedly increased risk of progression to acute myeloid leukemia (AML)." (PMID 41465537, 2025).
type 2 diabetes (3 papers, 2019 to 2021). "Another study found that under the condition of obesity, activation of the hepatic NFE2/miR-423-5p axis plays important roles in the progression of type 2 diabetes and NAFLD by repressing the FAM3A-ATP-Akt signaling pathway." (PMID 32351607, 2020). "A previous study showed that the transcription factor NFE2 binds to the promoter of the miR-423-5p precursor and positively regulates miR-423-5p expression in type 2 diabetes." (PMID 31455213, 2019).
lung adenocarcinoma (2 papers, 2011 to 2023). A carcinoma that arises from the lung and is characterized by the presence of malignant glandular epithelial cells. "The early-stage lung adenocarcinoma (LUAD) prognostic model was constructed through the cancer genome atlas (TCGA) database, and three target genes (MMP12, NFE2, HOXC8) were screened to calculate the risk score of early-stage LUAD." (PMID 36650426, 2023).
meningioma (2 papers, 2017 to 2018). A generally slow growing tumor attached to the dura mater. "POLR2A-mutant meningiomas do not exhibit mutations in other meningeal driver genes, such as NFE2, TRAF7, KLF4, AKT1, or SMO." (PMID 30279357, 2018). "NME1, NFE2, SFN, PTN, CALN1, GABRA5 and several components involved in neural differentiation and receptors associated with neural transmitter were also found to illicit an autoimmune response in the meningioma patients indicating that there could be some alterations in these components." (PMID 28938569, 2017).
myelofibrosis (2 papers, 2022 to 2025). A partial or complete replacement of the bone marrow stroma by fibrous tissue. "In more details, NFE2, SRSF2 and EZH2 were associated with secondary myelofibrosis, while SRSF2 and IDH1/2 were associated with AML/MDS transformations." (PMID 40533498, 2025).
pancreatic cancer (2 papers, 2023 to 2024). "We also found that pancreatic cancer patients with elevated expression of MAPK1, LRRFIP1, SP110, and NFE2 had a decreased rate of survival relative to patients with lower expression of these genes." (PMID 37627195, 2023).
thrombosis (2 papers, 2025). "Patients with NFE2 gene mutations had a higher incidence of pre-diagnosis thrombosis(39.0% vs 22.0%, P=0.012)and pre-diagnosis arterial thrombosis(36.6% vs 20.4%, P=0.014)." (PMID 41339048, 2025).
viral infection (2 papers, 2010 to 2025). "To explore the relationship between eEF2 phosphorylation and NFE2, we employed an in vitro mouse fetal liver cell (FLC) culture system, a highly efficient platform for gene manipulation via viral infection." (PMID 40429942, 2025).
amyotrophic lateral sclerosis (1 paper, 2021). Amyotrophic lateral sclerosis (ALS) is a neurodegenerative disease characterized by progressive muscular paralysis reflecting degeneration of motor neurons in the primary motor cortex, corticospinal tracts, brainstem and spinal cord. "We then discuss these findings in the context of the oxidative stress observed in two neurodegenerative diseases, Parkinson’s disease (PD) and amyotrophic lateral sclerosis (ALS), and present current strategies for activating NFE2/NRF-dependent transcription." (PMID 35052512, 2021).
Bernard-Soulier syndrome (1 paper, 2025). Bernard Soulier syndrome (BSS) is an inherited platelet disorder characterized by mild to severe bleeding tendency, macrothrombocytopenia and absent ristocetin-induced platelet agglutination. "Genetic knock-out studies in Hoxa7-TPO cells recapitulate the key function of Klf1 and Nfe2 in red blood cell and platelet development, respectively, while disruption of the von Willebrand receptor gene Gp1ba recapitulates features of human Bernard-Soulier syndrome." (PMID 40775216, 2025).